TP53I13 (tumor protein p53 inducible protein 13)
Description:
May act as a tumor suppressor. Inhibits tumor cell growth, when overexpressed.
Synonyms: DSCP1
Tractability: Antibody: UniProt places it where antibodies can reach, with high confidence; UniProt predicts a signal peptide or a membrane-spanning region; its Gene Ontology location is reachable by antibodies, with medium confidence. PROTAC: ubiquitination databases record sites on it.
Gene: Protein-coding gene on chromosome 17 (29,566,052 to 29,573,164, forward strand). Ensembl gene ENSG00000167543.
Subcellular location: Cell membrane; Cytoplasm
Gene Ontology:
Molecular function: protein binding
Biological process: negative regulation of cell cycle; response to UV; response to xenobiotic stimulus
Cellular component: cytoplasm; plasma membrane
Genetic constraint (gnomAD): Loss-of-function variants: 27 observed, 33.5 expected, observed/expected ratio (o/e) 0.81, 90% interval 0.59 to 1.11. The upper end of that interval is the gene's LOEUF score, 1.11, which puts it in group 4 of 6, group 1 being the genes least tolerant of losing a copy. Missense variants: 533 observed, 475.51 expected, observed/expected ratio (o/e) 1.12, 90% interval 1.04 to 1.2. Synonymous variants: 229 observed, 193.76 expected, observed/expected ratio (o/e) 1.18, 90% interval 1.06 to 1.32.
Homologues: Orthologues: chimpanzee TP53I13 (99% identical), macaque TP53I13 (88% identical), pig TP53I13 (76% identical), dog TP53I13 (74% identical), guinea pig TP53I13 (72% identical), rabbit TP53I13 (72% identical), mouse Trp53i13 (70% identical), rat Tp53i13 (68% identical), tropical clawed frog tp53i13 (30% identical), zebrafish tp53i13 (25% identical), Drosophila melanogaster CG12093 (11% identical), Caenorhabditis elegans Y41C4A.8 (9% identical).
Diseases named in the same sentence as TP53I13 in open-access papers:
TP53I13 is named in the same sentence as 25 diseases in open-access papers, as found by Europe PMC text mining. Sharing a sentence is not in itself a finding about the gene and the disease. The quoted sentences say what the papers report.
glioma (3 papers, 2022 to 2024). A benign or malignant brain and spinal cord tumor that arises from glial cells (astrocytes, oligodendrocytes, ependymal cells). "Similar results were obtained in glioma patient samples from Nantong University Affiliated Hospital, where high TP53I13 expression was associated with poor survival." (PMID 36275718, 2022). "Glioma patients’ TP53I13 levels were directly associated with prognosis in Multivariate Cox analysis." (PMID 36275718, 2022). "TP53I13 expression is also associated with a poor prognosis in glioma patients." (PMID 36275718, 2022). "Patients harboring IDH mutation expressed high TP53I13 levels (red and green) and had poor survival outcomes, further confirming that TP53I13 could be a potential prognostic biomarker for gliomas." (PMID 36275718, 2022). "In conclusion, our results suggest that TP53I13 may serve as a potential diagnostic and treatment biomarker for glioma patients." (PMID 36275718, 2022). "Further, the mechanism associated with TP53I13 in glioma was investigated." (PMID 36275718, 2022). "A gene set enrichment analysis (GSEA), STRING, and GeneMANIA were used to investigate TP53I13 functions in gliomas." (PMID 36275718, 2022). "STRING and GeneMANIA were used to investigate the function of the PPIs with TP53I13 levels in gliomas." (PMID 36275718, 2022). "We analyzed the CGGA and TCGA databases for relationships between TP53I13 expression and glioma subgroups." (PMID 36275718, 2022). "A combination of WHO grade, age, sex, and TP53I13 was an independent prognostic factor in glioma patients, based on the results of the study." (PMID 36275718, 2022). "To further assess the fundamental mechanisms of TP53I13 in glioma, we evaluated the relationships between lymphocytes and TP53I13 expression in cells using TCGA, CGGA, and TIMER databases." (PMID 36275718, 2022). "Nevertheless, with a detailed bioinformatics analysis, we laid the groundwork for understanding TP53I13’s role in gliomas." (PMID 36275718, 2022). "In glioma patients who had high levels of TP53I13 expression, the levels of M2 macrophages increased significantly, according to the quanTiseq algorithm." (PMID 36275718, 2022). "For evaluating the link between the glioma patients and TP53I13 expression at the single-cell level, scTIME and TISCH databases were analyzed." (PMID 36275718, 2022). "GBM cells expressed the highest level of TP53I13, while LGG cells expressed the highest level of TP53I13, indicating a better prognosis of glioma." (PMID 36275718, 2022). "In order to better understand TP53I13’s role in the pathogenesis of gliomas, in vivo models need to be validated." (PMID 36275718, 2022). "There are 15 genes with differential expression in glioma and normal tissues with high and low levels of TP53I13, as shown by a heatmap." (PMID 36275718, 2022). "Higher tumor grades had a worse prognosis, and TP53I13 expression increased as the glioma progressed in all the glioma patients." (PMID 36275718, 2022). "Further, we investigated the link between immune cell infiltration and the TP53I13 protein expression with radiotherapy status and tumor types in glioma patients using TIMER, CIBERSORT, quanTiseq, and the xCell algorithm." (PMID 36275718, 2022). "Nevertheless, TP53I13 role and expression in the emergence and progression of glioma (low-grade glioma and glioblastoma) are yet to be identified." (PMID 36275718, 2022). "Further study of the potential prognostic value of TP53I13 in gliomas, a survival analysis including OS and DSS was conducted on patients divided based on their clinical characteristics." (PMID 36275718, 2022). "In order to examine the molecular mechanism of TP53I13 in gliomas as well as its relationship to other genes involved in glioma, the mRNA sequence data retrieved from TCGA database was analyzed using the functional module of LinkedOmics." (PMID 36275718, 2022). "In glioma samples, TP53I13 expression appears to be lower than in paracancerous or cancerous tissues." (PMID 36275718, 2022).
glioma (continued). "In glioma patients with high TP53I13 expression (red and green), poorer survival outcomes were observed similarly to IDH mutation status." (PMID 36275718, 2022). "We also investigated the independent prognostic value of TP53I13 on 159 glioma samples obtained from the Affiliated Hospital of Nantong University." (PMID 36275718, 2022). "Multiple databases were consulted to evaluate and assess the expression of TP53I13, such as the Cancer Genome Atlas (TCGA), the Chinese Glioma Genome Atlas (CGGA), GeneMANIA, and Gene Expression Profiling Interactive." (PMID 36275718, 2022). "Accordingly, TP53I13 plays a significant role in the development of gliomas, and it can be used as a biomarker for glioma prognosis prediction." (PMID 36275718, 2022). "GEPIA was used to investigate TP53I13 expression, and the results reveal that TP53I13 expression was low in normal tissues compared to gliomas such as LGG and GBM." (PMID 36275718, 2022). "Glioma cells with knockdown of TP53I13 expression exhibit reduced migration and invasion abilities and induce apoptosis." (PMID 36275718, 2022). "In order to improve survival prediction mapping for glioma patients, we integrated TP53I13 expression levels with other prognostic factors." (PMID 36275718, 2022). "We evaluated TP53I13’s prognostic value in glioma patient samples retrieved from TCGA regarding 1-year survival, 3-year survival, and 5-year survival." (PMID 36275718, 2022). "The results show an increased TP53I13 expression in CAF, elevated TP53I13 expression in CAF may be associated with poor prognostic outcomes in glioma patients." (PMID 36275718, 2022). "Second, TP53I13 functions and mechanisms in glioma need to be further explored." (PMID 36275718, 2022). "As a result of these results, TP53I13 may become a potential biomarker for the treatment of gliomas in the future." (PMID 36275718, 2022). "It is likely that the levels of TP53I13 expression may vary in tumor and paracancerous groups; hence, we explored this conjecture by analyzing DElncRNAs, DEmRNAs, and DEmiRNAs in glioma samples." (PMID 36275718, 2022). "As a result of these findings, TP53I13 might represent a new biomarker of immune infiltration and prognosis in patients with gliomas." (PMID 36275718, 2022). "Therefore, we confirmed this conjecture by identifying the DEmRNAs, DElncRNAs, and DEmiRNAs in glioma tissues with high and low TP53I13 expression and adjacent normal tissue using samples from the TCGA database." (PMID 36275718, 2022). "The analysis of multivariate Cox showed that TP53I13 might be an independent prognostic marker of glioma." (PMID 36275718, 2022). "Our results reveal a close correlation between TP53I13 and gliomas." (PMID 36275718, 2022). "Thus, we aim to use comprehensive bioinformatics analyses to investigate TP53I13 and its prognostic value in gliomas." (PMID 36275718, 2022). "It has been shown that TP53I13 expression is higher in patients with gliomas." (PMID 36275718, 2022). "Additionally, Nantong’s Affiliated Hospital provided 183 patient samples, confirming TP53I13’s prognostic value in predicting glioma outcomes." (PMID 36275718, 2022). "To learn more about TP53I13’s prognostic value in gliomas, we conducted our study." (PMID 36275718, 2022). "A TCGA and CGGA database containing glioma samples was examined for TP53I13 mRNA expression." (PMID 36275718, 2022). "Taking these results together, it appears that glioma patients with low TP53I13 expression could have a higher survival rate." (PMID 36275718, 2022). "This study has enhanced the understanding of TP53I13 expression in glioma patients." (PMID 36275718, 2022). "Therefore, it would seem that TP53I13 could be a potential therapeutic target and prognostic biomarker for gliomas." (PMID 36275718, 2022). "Therefore, we hypothesize that the occurrence and progression of glioma could be related to the high TP53I13 expression." (PMID 36275718, 2022).
glioma (continued). "Finally, the AUC values of Siglec15, CTLA-4, PD-L1 and TP53I13 were compared, and the ROC curve was calculated to evaluate whether TP53I13 could predict the immune infiltration of glioma." (PMID 36275718, 2022). "Further, TP53I13 expression could affect the survival outcomes in glioma patients." (PMID 36275718, 2022). "TP53I13 overexpression is significantly correlated with IDH status, age, chemotherapy, 1p/19q codeletion, and tumor grade in glioma patients." (PMID 38460946, 2024). "The proportion of 22 types of immune cells in glioma samples retrieved from CGGA and TCGA databases was sorted and analyzed by CIBERSORT to explore the relationship between TP53I13 expression and tumor immune microenvironment." (PMID 36275718, 2022). "According to CGGA and TCGA glioma patient samples, IDH wild-type patients expressed higher levels of TP53I13 than IDH mutant patients." (PMID 36275718, 2022). "Gliomas like LGG and GBM exhibit significant expression of TP53I13." (PMID 36275718, 2022). "Furthermore, TP53I13 was shown to be expressed at higher levels in AC-like malignant cells and malignant cells according to the TSICH database, which further emphasized the malignancy of glioma severity and the necessity to find a biomarker for glioma treatment." (PMID 36275718, 2022).
acute lymphoblastic leukemia (1 paper, 2022). Leukemia with an acute onset, characterized by the presence of lymphoblasts in the bone marrow and the peripheral blood. "In the presence of N4-Eru, elevated levels of TP53I13 serve as a tumor suppressor in T-cell acute lymphoblastic leukemia (ALL) cells (Jurkat cells)." (PMID 36275718, 2022).
bladder cancer (1 paper, 2022).
glioblastoma (1 paper, 2022). The most malignant astrocytic tumor (WHO grade IV). "On the contrary, poor survival was observed TP53I13 expressing tumors including like Uveal Melanoma (UVM; P = 3.6e-03), LGG (P = 1.9e-17), KIRC (P = 3.8e-06), kidney chromophobe (KICH; P = 1.5e-02), and glioblastoma (GBM; P = 2.6e-02)." (PMID 36275718, 2022).
uterine corpus endometrial carcinoma (1 paper, 2022). A endometrial carcinoma (disease) that involves the body of uterus. "TP53I13 expression in cancers like PAAD (P = 1.4e-02) and uterine corpus endometrial carcinoma (UCEC; P = 3.3e-02) had good disease-specific survival (DSS)." (PMID 36275718, 2022).
tumor (4 papers, 2009 to 2023). "Based on previous studies, it is likely that overexpression of TP53I13 in most normal tissues suppresses tumor formation." (PMID 36275718, 2022). "It was also found that increased expression of TP53I13 was significantly correlated with PRS type, status, 1p/19q codeletion status, IDH mutation status, chemotherapy, age, and tumor grade." (PMID 36275718, 2022). "A significant correlation was found between TP53I13 expression and tumor grade, chemotherapy, co-delete of 1p and 19q, and IDH mutations." (PMID 36275718, 2022). "Further, TP53I13 expression was studied in tissue samples obtained from Nantong University Affiliated Hospital, and the results revealed that TP53I13 expression was higher in tumor tissues than in normal tissues." (PMID 36275718, 2022). "An analysis of bioinformatics revealed higher TP53I13 expression in tumor tissues." (PMID 36275718, 2022). "An algorithmic approach combining quanTiseq, xCell, and TIMER was employed to determine whether TP53I13 expression correlates with tumor immune lymphocytes." (PMID 36275718, 2022). "TP53I13 overexpression is suggested to impede tumor cell growth." (PMID 36275718, 2022). "On the other hand, tumor tissues expressed TP53I13 at a higher level than normal tissues." (PMID 36275718, 2022). "Further TP53I13 expression was higher in neutrophils, which suggests that TP53I13 may promote tumor metastasis via neutrophils." (PMID 36275718, 2022). "Therefore, CIBERSORT, quanTiseq, xCell, and TIMER were used to investigate the correlation between TP53I13 expression and various tumor-infiltrating immune cells." (PMID 36275718, 2022). "The expression of TP53I13 was higher in tumor samples compared to normal samples." (PMID 36275718, 2022). "Levels of TP53I13 were up-regulated over 1.5-fold in Ad5 E1-TC over Ad12 E1-TC and could be exerting a tumour suppressor effect in these cells, as there is in vitro evidence that such up-regulation retards cancer cell growth." (PMID 19200380, 2009). "Therefore, an increase in TP53I13 expression could impede tumor growth in hematological cancers." (PMID 36275718, 2022).
cancer (2 papers, 2009 to 2022). A tumor composed of atypical neoplastic, often pleomorphic cells that invade other tissues. "TP53I13 expression in cancers like GBM (P = 4.8e-02), KICH (P = 3.2E-02), KIRC (P = 6.9e-08), LGG (P = 1.4e-16), and UVM (P = 8.1e-03) had poor DSS." (PMID 36275718, 2022). "A significant role in the TME might be played by the upregulation of TP53I13 expression in cancer and infiltrating immune cells." (PMID 36275718, 2022).
hematological tumors (1 paper, 2022). "Interestingly, upregulated level of TP53I13 helps to confirm that N4-Erucoyl spermidine could play a significant role in inhibiting hematological tumors." (PMID 36275718, 2022).
TP53I13 also shares sentences with these, for which no sentence is quoted: alcohol dependence (2 papers); Alzheimer disease (2); Anxiety (2); dementia (2); depression (2); encephalomyopathy (2); bladder urothelial carcinoma (1); cholangiocarcinoma (1); diffuse large B-cell lymphoma (1); low grade glioma (1); lymphoid neoplasm (1); paraganglioma (1); pheochromocytoma (1); skin cutaneous melanoma (1); T-cell acute lymphoblastic leukemia (1); thymoma (1); uveal melanoma (1).